CXCL9 (C-X-C motif chemokine ligand 9)
Diseases named in the same sentence as CXCL9 in open-access papers (continued):
Sharing a sentence is not in itself a finding about the gene and the disease.
tumor (continued). "Given the increase in Cxcl9/10 mediated signals from mdTAMs following anti-PD-L1 treatment, we hypothesised that Cxcr3-expressing T cells would localise to the tumour core, where mdTAMs were enriched." (PMID 40523200, 2025). "However, the TME of IL-1α KO tumors showed higher expression of CXCR3 ligands, such as CXCL9/10, which can attract anti-tumor CXCR3+ CTL, and Th1 lymphocytes, and NK cells." (PMID 38612760, 2024). "CXCL9 plays an important role in tumor immunosurveillance and antitumor immunity." (PMID 39334887, 2024). "Additionally, IFN-γ directly induces tumor cell death through anti-proliferative mechanisms and impedes intra-tumoral angiogenesis by inducing chemokines, such as C-X-C motif chemokine ligand 9 (CXCL9), CXCL10, and CXCL11." (PMID 39085965, 2024). "CXCL9 released by DCs increased the infiltration of CD8 + T cells at the tumor site." (PMID 39578426, 2024). "In addition, the concurrent use of intramuscular CXCL9/10 and intraperitoneal anti-PD-1 administration successfully inhibited tumor growth." (PMID 39273452, 2024). "We found that high expression of CXCL9 in the TNBC TME, whether at the center of the tumor or at the front of the invasion, was associated with better prognosis." (PMID 38957805, 2024). "Consistently, the CXCL9 expression by cDC1 and CXCR3 expression by CD8+ T cells were upregulated in tumors from hsBCL9z96-treated CT26 tumor-bearing mice, as well as from MC38 tumor-bearing Bcl9/Bcl9l deficiency mice." (PMID 38811552, 2024). "B cells can produce chemokine CXCL9 and lymphotoxin, and recruit T cells to tumor tissues." (PMID 39840050, 2024). "In addition, an effector T-cell gene signature in the tumor defined as the expression of CXCL9, PD-L1 and IFN-γ messenger RNA has been proposed as possible predictive marker of ICI efficacy." (PMID 39596334, 2024). "Notably, M1 macrophages induced by IL-9 recruit anti-tumor immune cells into the tumor tissue through the chemoattractant macrophage chemokines CCL3/4 and CXCL9/10, thereby triggering anti-tumor immunity." (PMID 38892411, 2024). "In the present study, we systematically profiled the cellular components of the TME in TNBC by scRNA-seq data, as well as identified signature genes of pro-inflammatory immune cells, including CXCL13+ tumor-reactive T cells, activated T cells, effector T cells, CXCL9+ TAMs, NK cells, and cDC1." (PMID 38533207, 2024). "The limited infiltration of T cells into the tumor microenvironment may be downstream of the epigenetic silencing of key chemokines such as CXCL9 and CXCL10, which encompasses inhibitory histone modification and DNA methylation." (PMID 38665224, 2024). "As a result, targeting CXCR3 signaling pathways by CXCL9/10 could be a promising anti-tumor strategy." (PMID 38953994, 2024). "In addition, engineered CAR-T cells expressing high levels of CXCL9 attracted endogenous CD8 T cells to the tumor site and achieved remarkable tumor control in preclinical models." (PMID 39242595, 2024). "In addition to CCL5/IFNG expression in the diagnostic tumor biopsy our study also discloses the potential role of serum CCL5 and CXCL9 as early biomarkers of response to neoadjuvant treatment with anti-HER2 antibodies." (PMID 38167224, 2024). "CXCL9 has the ability to induce chemotaxis in T cells and NK cells, directing them to sites of inflammation to participate in immune and inflammatory responses, and plays a role in tumor immunosurveillance and anti-tumor immunity." (PMID 39334887, 2024). "The expression of CXCL9 chemokine in the tumor bed has been reported to enhance the proximity of CD8+ T cells to IL-12-producing cDC1s and consequently promote cytokine exposure and T-cell effector functionalities due to the ability of IL-12 to promote T-cell proliferation." (PMID 38360737, 2024). "CXCL9/10-DC vaccination induced an initial recruitment of effector T cells, predominantly at the leading tumor edge, suggesting that tumor killing may be initiated at the tumor leading edge." (PMID 38518770, 2024).
tumor (continued). "Moreover, in these individuals, increased levels of CXCL9 and CXCL10 were linked to improved OS and a greater presence of CD8+ T cells within the tumor." (PMID 39273452, 2024). "Notably, the inhibition of tumor growth and improved survival in C5aR−/− mice was abrogated by depleting CXCL9, suggesting that the enhanced antitumor function by C5aR deletion depends on CXCL9-mediated recruitment of CD8+ T cells." (PMID 38098230, 2024). "Although CXCL9/10-DC monotherapy promotes T cell infiltration to the tumor margin, combination therapy with anti-PD-1 enhances T cell infiltration into the tumor and augments their proliferation and activity, resulting in the establishment of tumor-specific immunity." (PMID 38518770, 2024). "We hypothesized that AAV delivery and restoration of CXCL9 as a “call-and-receive” signal for T lymphocytes within the tumor microenvironment (TME) would enhance their recruitment and infiltration in the tumor." (PMID 38997283, 2024). "Furthermore, Tregs expressing CXCR3 co-localize with DCs producing CXCL9 in tumors, which affects the presentation of tumor-derived antigens and dampens the activity of anti-tumor CD8+T cells." (PMID 39290699, 2024). "As illustrated, tumor cell‐intrinsic Sin3B loss did not enhance the expression levels of Cxcl9 and Cxcl10 in either CAFs or macrophages within the TME." (PMID 39316363, 2024). "In addition to facilitating effector T cell infiltration into the tumor, the CXCL9/CXCL10/CXCR3 signaling cascade is required for optimal T cell activation." (PMID 38518770, 2024). "Recently, CXCL9 was investigated as a critical chemokine that can recruit and activate immune cells, particularly T lymphocytes, to the tumor microenvironment, thereby enhancing anti-tumor immunity in TNBC." (PMID 39695149, 2024). "Another environmental cue being investigated is the CXCR3 pathway as a significant axis of immunotherapy response that regulates the infiltration and spatial positioning of T cells near APCs expressing the ligands CXCL9/10/11 within the murine and human tumor microenvironment (TME)." (PMID 39211052, 2024). "IFN-γ can induce tumor cell death and trigger the release of a large number of cytokines, such as CXCL9, CXCL10, and CXCL11, thereby further recruiting NK cells and macrophages to the tumor microenvironment and inducing a non-specific anti-tumor immune response." (PMID 38534538, 2024). "Notably, immunofluorescence analysis of tumors from OC patients revealed significantly lower levels of CXCL9 in tumor tissues compared to adjacent normal regions." (PMID 38098230, 2024). "In addition, CXCL9 was used for prognostic clinical tumor outcomes together with Phosphoprotein 1 (SPP1 or osteopontin) in neck squamous cell carcinomas (HNSCCs)." (PMID 38542388, 2024). "We next depleted CXCL9 in WT and C5aR−/− tumor-bearing mice." (PMID 38098230, 2024). "Moreover, in our investigation into Gsdmc downregulation, we discovered a notable increase in Cxcl9 expression, crucial for recruiting anti‐tumor immune cells like cytotoxic T cells and NK cells via the CXCL9/CXCR3 axis." (PMID 39297408, 2024). "Intriguingly, we observed that depletion of CXCL9 also led to a significant reduction in the abundance of tumor-associated macrophages (data not shown)." (PMID 38098230, 2024). "Additionally, an analysis of the tumor homogenates from treated vs. control mice via a multiplex cytokine panel highlighted intra-tumoral increases in CXCL9 and CXCL10." (PMID 38339310, 2024). "For example, it has been well documented that CXCL9/10/11 could effectively recruited infiltrating CD8+ T cells into the tumor microenvironment, which were regarded as potential cancer immune therapy targets." (PMID 38232115, 2024). "Studies have proved that the expression levels of CXCL10 and CXCL9 in tumor may be correlated with a poor prognosis of overall survival." (PMID 38448514, 2024). "Antibodies against galectin-9, were shown to enhance CXCL9 production by tumor cDC1s." (PMID 38418707, 2024).
tumor (continued). "Interestingly, CXCL9 and CXCL10 produced by tumor-associated macrophages (TAMs) have also been correlated with enhanced anti-programmed death-ligand 1 (PD-L1) response rates." (PMID 39596815, 2024). "We report that in addition to attracting CXCR3+ T cells to tumor sites a key role of CXCL9 and CXCL10 is in inducing a self-feeding feedback loop that accelerates effector/cytotoxic activities of both CD4+ and CD8+ T cells while downregulating immunoregulatory protein TIM3." (PMID 39474427, 2024). "The CXCL9/CXCL10-CXCR3 is another axis with anti-tumor properties." (PMID 39114657, 2024). "Given that Cxcl9 and Cxcl10 share the same receptor CXCR3, we hypothesized that Sin3B loss recruited CD8+ T cells into the tumor milieu predominantly through the CXCL9/10‐CXCR3 axis." (PMID 39316363, 2024). "In addition, CXCL9 was evident as its expression can also be hijacked by TNBC cells to promote tumor growth and metastasis." (PMID 39695149, 2024). "Thus, when appropriately targeted, cancer cells themselves can be induced to promote the elaboration of chemokines, such as CXCL9/10, that promote an anti-tumor response." (PMID 38339310, 2024). "Collectively, these findings demonstrated that high CXCL9 expression was indicative of a tumor immune‐active microenvironment, which might enhance the sensitivity of tumors to ICIs." (PMID 38434763, 2024). "Prominently, only CXCL9+ macrophages were frequently neighboured by tumour cells." (PMID 38570491, 2024). "Diverse components of the interferon-enriched community including LAMP3+ DC, CCL19+ fibroblast, CXCL9+ macrophage, and mesenchymal-derived interferon states confer favorable responses to immunotherapy and form different ecosystems between tumor, adjacent normal, and healthy normal tissues." (PMID 38744958, 2024). "Specially, iCAFs interacted with tumor-infiltrating T cells through CXCL9/10/11-CXCR3, CXCL12-CXCR4, and CCL19-CCR7, suggest that these iCAFs might recruit T cells and shape the immune landscape of AEG TME through multiple chemotactic regulation." (PMID 38182569, 2024). "In the tumor, IFNγ stimulates the production of CXCL9 by tumor and stromal cells, resulting in increased infiltration of CXCR3+ (CXCL9 receptor) cytotoxic immune cells (such as CD8+ T cells and Natural Killer cells) into the tumor that promotes its eradication." (PMID 38698860, 2024). "Moreover, anti-tumor chemokine genes including CXCL9, CXCL10, CXCL11 and CXCL13 expressed higher in the high-necroptosis cohort." (PMID 39247606, 2024). "One mechanism through which K17 downregulates T cell infiltration could be through the suppression of CXCL9 production in macrophages through tumor cell-macrophage interactions." (PMID 38730319, 2024). "In a recent study, the collaborative actions of CXCL9 and SPP1 (CXCL9:SPP1) were found to collectively dictate the polarity of tumor-associated macrophages (TAMs) within the TME, exerting profound effects on tumor progression and treatment responses." (PMID 38217023, 2024). "As CXCL9 is a small, secreted chemokine, we wanted to determine if signal expression was still focal to the tumor or could be detected in contralateral brain and/or systemically." (PMID 38014191, 2023). "To identify CXCL9/10-secreting cell populations in tumors of triple-treated mice, we performed a flow cytometry experiment where myeloid cells turned out to be important CXCL9/10 producers, including in the unirradiated tumor, consistent with previous findings." (PMID 37045833, 2023). "Tumor cells also underwent significant changes after mANK-101 treatment, including increased expression of proinflammatory chemokines CXCL9 and CXCL10, and upregulation of genes responsible for antigen processing and MHC I presentation, likely mediated by IFN-γ signaling through STAT1." (PMID 38063196, 2023).
tumor (continued). "Interestingly, our model strongly implicates CXCL9 in the prediction of t cells, which is traditionally believed to be secreted by tumor cells themselves or TAMs to drive t cell recruitment." (PMID 36906603, 2023). "The elevated levels of Ifng further induce antitumor immune activity in tumors, leading to increased CXCL9 expression from tumor cells; CXCL9 then recruits CXCR3+ immune cells, such as cytotoxic CD8+ T cells and NK cells, into cancers to increase effector immune cell infiltration." (PMID 37253006, 2023). "CXCL9 is induced in antigen presenting cells in response to IFNγ, which amplified engraftment of tumor infiltrating lymphocytes and helped establish the ‘‘hot’’ tumor immunophenotype." (PMID 37365574, 2023). "Moreover, CXCL9, as one of the momentous chemoattractants for leukocytes, B cells, and T cells, can serve as a tumor suppressor." (PMID 36845675, 2023). "It suggests that RT enhances CD8+ T cell recognition of tumors that may be due to CXCL9/10-mediated recruitment of T lymphocytes since we demonstrated that RT also induced CXCL9/10 expression in tumor cells." (PMID 36688994, 2023). "Further, CXCL9 was positively related to CCL4, CCL5, CXCL10, and CXCL11 in UCEC, which are associated with DC, NK, and T cell recruitment and play an essential role in suppressing tumor growth and improving prognosis." (PMID 36845675, 2023). "Indeed, CXCL-9 overexpression leads to the recruitment of T-cells as well as the inhibition of tumor growth and metastasis in an animal experiment." (PMID 37958417, 2023). "In different cancers, CXCL9 serves as a tumor suppressor or promoter, as it may regulate cellular processes in a specific manner through different regulatory networks." (PMID 36845675, 2023). "Furthermore, in animal models, CXCL9 overexpression promotes tumor T‐cell accumulation and improves immune checkpoint blockade therapy response in previously resistant mice." (PMID 37525619, 2023). "In addition, the expression of CXCL9 in tumour tissues of CTRL + Vehicle, NE + anti-PD-1 mAb + Vehicle and anti-PD-1 mAb + Vehicle groups was further detected by western blot." (PMID 36646807, 2023). "Seitz found that CXCL9 inhibited tumor growth and promoted anti PD-L1 treatment of ovarian cancer." (PMID 36798787, 2023). "Furthermore, the specific molecular mechanisms and exact functions of CXCL9 anti-tumor effects in UCEC need to be further explored and validated by in vivo and in vitro experiments." (PMID 36845675, 2023). "In this work, we propose a tumor-specific expression strategy utilizing tumor-specific gene nanomedicines to drive tumor cells to secrete CXCL9 and anti-PD-L1 scFv (αPD-L1), thereby forming high intratumoral concentrations of CXCL9 and αPD-L1 for T-cell recruitment and PD-L1 blockade, respectively." (PMID 37031188, 2023). "Experimental evidence suggests that tumor-infiltrating cDC1s promote tumor control in various ways, including the production of chemokines such as C-X-C motif chemokine ligand 9 (CXCL9) and C-X-C motif chemokine ligand 10 (CXCL10), which recruit CD8+ T cells to the tumor site." (PMID 38012715, 2023). "In addition, we transfected tumour cells with CXCL9-shRNA lentivirus or scramble-shRNA lentivirus (NC) to further determine the role of CXCL9." (PMID 36646807, 2023). "Conversely, previous studies also identified that CXCL9 might act directly on multiple types of tumor cells expressing the CXCR3 receptor to improve epithelial-mesenchymal transition (EMT) and cell migration." (PMID 36845675, 2023). "Importantly, NPTyr-C9AP treatment increased the percentages of tumor-infiltrating CD3+ T cells to 21.7% of CD45+ lymphocytes due to the synergistic effects of intratumoral expression of CXCL9 and αPD-L1." (PMID 37031188, 2023). "CXCL9, also known as INF gamma (MIG) -induced monocytes, can be produced in inflammatory conditions by antigen-presenting cells (e.g., dendritic cells or macrophages) or tumor cells in the tumor microenvironment." (PMID 36845675, 2023).
tumor (continued). "Tumor cell gene expression also changed significantly in mANK-101–treated animals, with increased Stat1, Cxcl9, and Cxl10 (all consistent with IFN-γ signaling), as well as increases in Cd74, MHC alleles, and proteasome components, indicating increased antigen processing and presentation." (PMID 38063196, 2023). "In non-tumor-bearing mice, 20–50% of cDC1s were producing Cxcl9 in the dLN, spleen and pancreas." (PMID 36472588, 2023). "The bioinformatics analysis was carried out to state that the CXCL9 expression was remarkably upregulated in UCEC tumor, compared with control ones based on the TCGA+GTEx dataset (P< 0.0001), TCGA dataset (P=0.0003), GSE36389 (P=0.014) and tissues of our validation cohort (P= 0.011)." (PMID 36845675, 2023). "We, therefore, propose that serum CXCL10 concentrations may serve as a surrogate for tumor immune subtypes and that levels may fluctuate with serum CXCL9 concentrations, reflecting the extent of immune reconstitution by anti-angiogenic therapy." (PMID 37880538, 2023). "The differential expression of Cxcl10 and Cxcl9 in tumor vs. spleen likely reflects different composition of myeloid cells and raises the possibility that the chemokines may play a differential role in the TEFF vs. TEX fate choice." (PMID 36472588, 2023). "CXCL9 facilitates the infiltration of effector T cells and NK cells into the tumor." (PMID 37046739, 2023). "Taken together, these results demonstrated that NPSur-C9AP could be used as a universal gene nanomedicine to enhance T-cell recruitment and activation in multiple tumors for enhanced immunotherapy via tumor-specific coexpression of CXCL9 and αPD-L1." (PMID 37031188, 2023). "Stimulator of interferon genes (STING) upregulation in tumor APCs triggers chemokine expression, notably C-X-C motif chemokine ligand 9 (CXCL9) and CXCL10 by DCs, and CXCL10 and CXCL11 by tumor-associated macrophages (TAMs), folstering intratumoral T cell trafficking." (PMID 38044445, 2023). "Studies have shown that the intratumoral abundance of CXCL9, 10 or 11 determines the numbers of tumor-infiltrating T cells, whereas most tumors restrain the expression of CXCL9, 10 or 11 to reduce T-cell recruitment, leading to the frequent failure of PD-1/PD-L1 blockade therapy." (PMID 37031188, 2023). "Notably, NPTyr-C9AP that coexpressed CXCL9 and αPD-L1 exhibited synergistic antimelanoma effects, and the tumor growth inhibition rate reached 84.3%." (PMID 37031188, 2023). "However, how K17 expression in tumor cells leads to decreased CXCL9 production in immune cells has yet to be determined." (PMID 38140561, 2023). "METTL3/14 knockout in CRC enhanced the response to anti–PD-1 therapy in constructed Patient-Derived Xenograft (PDX) mice by increasing the infiltration of cytotoxic CD8+ T cells into the tumor cell and a marked increase in the concentration of IFN-c, Cxcl9, and Cxcl10 in the tumor microenvironment." (PMID 36960074, 2023). "In summary, we have developed tumor-specific gene nanomedicines to specifically drive different tumor cells to coexpress CXCL9 and αPD-L1, which provide a solution for addressing both the lack of tumor-infiltrating T cells and the insufficient tumor enrichment of αPD-L1 inhibitors in ICB therapy." (PMID 37031188, 2023). "CD11b+ Gr-1int myeloid cells from Nlrp3−/− mice produce higher levels of C–C motif chemokine ligand 5 (CCL5) and C-X-C motif chemokine ligand 9 (CXCL9) that are responsible for elevated recruitment and activation of NK cells in tumor microenvironment resulting in a lower number of lung metastasis." (PMID 36932407, 2023). "Increased infiltration of CAR T-cells into tumor.Reduction in tumor infiltrating Tregs.Suppression of co-inhibitory receptor (PD-1 & LAG3) expression on T cells.Promotes expression of T-cell recruiting chemokines in tumor cells (CXCL9, CXCL10) and CXCR3 receptors on CAR T cells." (PMID 36949946, 2023).